UCA1 (urothelial cancer associated 1)
Diseases named in the same sentence as UCA1 in open-access papers (continued):
Sharing a sentence is not in itself a finding about the gene and the disease.
ovarian carcinoma (58 papers, 2016 to 2025). A malignant neoplasm originating from the surface ovarian epithelium. "In ovarian cancer, the lncRNA urothelial carcinoma associated 1 (UCA1) was reported to mediate cisplatin resistance via transfer in tumor cells-derived exosomes." (PMID 39403602, 2024). "The lncRNA urothelial carcinoma associated 1 (UCA1) was enriched in ovarian cancer-derived exosomes, and it was reported to mediate gefitinib resistance by sequestering miR-143 to increase FOSL2 expression." (PMID 39403602, 2024). "Long non-coding RNA urothelial carcinoma-associated 1 (UCA1) has been proven to be involved in the pathogenesis of various diseases in humans, including various types of ovarian diseases, such as ovarian cancer." (PMID 36232884, 2022). "It has been reported that lncRNA UCA1 (urothelial cancer associated 1) is significantly upregulated in PTX-resistant ovarian cancer tissues and cell lines and confers ovarian cancer resistance to PTX." (PMID 34512721, 2021). "In terms of UCA1, the elevated expression was shown to enhance cell migration, invasion and cisplatin resistance of ovarian cancer, and the lincRNA activates Hippo-Yes-associated protein (YAP) signaling in ovarian cancer." (PMID 34681900, 2021). "It has been confirmed that seRNA from urothelial cancer associated 1 (UCA1) promotes ovarian cancer development through interacting with angiomotin (AMOT) to activate yes-associated protein (YAP) signaling." (PMID 32278350, 2020). "The majority of these results of drug resistance were from in vitro studies, whereas clinical data was available only in ovarian cancers where high lncRNA UCA1 expression was associated with the response to platinum-based chemotherapy." (PMID 28969100, 2017). "Additionally, UCA1 is associated with other pathways that can promote cancer pathogenesis and therapy resistance, such as cisplatin resistance in ovarian cancer and additional solid tumors." (PMID 35454885, 2022). "Interestingly, our analysis did not identify lncRNAs that had previously been reported to be associated with ovarian cancer, such as UCA1, HOTAIR, XIST, or H1913." (PMID 33499129, 2021). "Association between UCA1 and metastatic process was also reported for epithelial ovarian cancer." (PMID 29147648, 2017). "The long non-coding RNA UCA1 has been demonstrated to actively contribute to paclitaxel (PTX) resistance in ovarian cancer, where its persistent expression is crucial for sustaining the chemoresistant phenotype." (PMID 41303609, 2025). "The long non-coding RNA (lncRNA) urothelial carcinoma-associated 1 (UCA1) is overexpressed in paclitaxel-resistant cells, and UCA1 expression was shown to correlate to the oncolytic effects of OVV in various primary ovarian cancer cell lines." (PMID 38558795, 2024). "For instance, the lncRNA urothelial cancer-associated 1 (UCA1), which is driven by a SE, is overexpressed in ovarian cancer and leads to tumorigenesis through YAP activation." (PMID 38763947, 2024). "GAS5 has been reported to function as a tumor suppressor-like gene, that can block ovary cancer progression, whereas UCA1 serves as a potential novel biomarker and therapeutic target for ovarian cancer." (PMID 35901079, 2022). "LncRNA UCA1 reduced cisplatin response of OAW42 ovarian cancer cells via direct sponging to miR-27a-5p and decreasing the expression of UBE2N levels, resulting in the inhibition of BIM expression, a member of the Bcl-2 family to induce apoptotic death." (PMID 36105363, 2022). "LncRNA UCA1 upregulation was found in ovarian cancer tissues and paclitaxel-resistant ovarian cancer cells." (PMID 36105363, 2022). "For examples, UCA1 can function as a competing endogenous RNA (ceRNA) to sponge tumor suppressor gene-binding miRNAs, thus promote cancer development, such as ovarian cancer." (PMID 35901079, 2022). "Another study revealed that knockdown of UCA1 sensitized the paclitaxel-resistant ovarian cancer cells to paclitaxel treatment via induction of apoptosis." (PMID 36105363, 2022).
ovarian carcinoma (continued). "Paclitaxel resistance was restrained by inhibition of lncRNA UCA1 in paclitaxel-resistant ovarian cancer cells." (PMID 36105363, 2022). "Increased expression of lncRNA UCA1 was detected in the serum exosomes of cisplatin-resistant ovarian cancer patients." (PMID 36139487, 2022). "To conclude, this study unravels the function and mode of action of UCA1 in the response to treatment in ovarian cancer cells and therefore emphasizes on the pivotal roles of lncRNAs in mechanisms of response to treatment in cancer." (PMID 34160887, 2021). "In ovarian cancer cells, UCA1 can also induce ABCB1 expression though endogenous sponging of miR-129 to enhance PTX tolerance." (PMID 34512721, 2021). "To determine how UCA1 acts on the chemoresistance of ovarian cancer cells, we compared the transcriptomic profiles of OAW42‐R cells 3 days after transfection with sictrl or siUCA1 using microarrays." (PMID 34160887, 2021). "In ovarian cancer, UCA1 has been shown to directly interact with miR‐129 and thus control the expression of ABCB1 protein, leading to the resistance to paclitaxel." (PMID 34160887, 2021). "UCA1 has been involved in resistance to several chemotherapeutic drugs in different tumor types, including in ovarian cancer." (PMID 34160887, 2021). "The lncRNA UCA1 is upregulated in ovarian cancer and is detected in exosomes derived from the serum of ovarian cancer patients." (PMID 33996797, 2021). "In recent years, lncRNA UCA1 has also been found to be involved in cisplatin resistance in ovarian cancer and blood UCA1 levels are upregulated in patients after cisplatin treatment." (PMID 34512721, 2021). "In ovarian cancer cells, UCA1 can induce SIK2 expression via endogenous sponging of miR-654-5p and thus antagonize chemosensitivity to PTX." (PMID 34512721, 2021). "In this study, we have unraveled a new pathway through which UCA1 exerts oncogenic functions in ovarian cancer." (PMID 34160887, 2021). "We explored UCA1 expression levels in ovarian cancer tissues in publicly available data sets from two independent cohorts." (PMID 34160887, 2021). "Abnormal expression of UCA1 promotes the invasion and metastasis of ovarian cancer cells by up-regulating matrix metalloproteinase (MMP) 2 and MMP9." (PMID 34233576, 2021). "The lncRNA UCA1 promotes ovarian cancer cell chemoresistance by sponging miR-143 to activate FOSL2 Signaling Pathway." (PMID 31747939, 2019). "Wang F, etc found that lncRNA UCA1 affected platinum resistance in ovarian cancer by targeting the SRPK1/PI3K-Akt signaling pathway." (PMID 31391118, 2019). "Both of these two studies focused on exploring association between lncRNA UCA1 or MALAT-1 and OS in all human cancers, ovarian cancer is just one of them." (PMID 28118613, 2017). "Transcription factor HIF-1α enhances lncRNA UCA1 overexpression in bladder and ovarian cancer cells in a hypoxia-dependent manner by directly binding to the hypoxia response elements (HREs) of UCA1 promoter." (PMID 28969100, 2017). "Many lncRNAs, such as HOTAIR, H19, MEG3, and UCA1, have been recognized as key regulators of the occurrence and development of ovarian cancer." (PMID 29050257, 2017). "Our analysis reveals an inverse correlation between UCA1 and FAM171A2 expression, suggesting that UCA1-mediated oncogenic signaling may suppress FAM171A2-associated regulatory pathways, thereby enhancing drug resistance mechanisms in ovarian cancer cells." (PMID 41303609, 2025). "For example, by binding to the 3′-UTR of FOS-like 2 (FOSL2), miR-143 can negatively regulate FOSL2 expression, suggesting that the UCA1/miR-143 axis may have potential therapeutic value for the treatment of cisplatin resistance in ovarian cancer patients." (PMID 36717926, 2023). "UCA1 accelerated cisplatin resistance via miR-27a-5p/UBE2N/BIM axis in ovarian cancer cells." (PMID 36105363, 2022). "LncRNA UCA1 is activated by SE in cases of ovarian cancer, promoting tumor development." (PMID 35311149, 2022).
ovarian carcinoma (continued). "UCA1 overexpression drives ovarian cancer development by activating the Hippo–YAP pathway." (PMID 35454885, 2022). "Importantly, these two studies evidenced that the ectopic expression of UCA1 or Linc00161 suppressed the tumorigenicity of ovarian cancer and reduced the cytotoxic effects of cisplatin in a tumor xenograft murine model." (PMID 34204094, 2021). "One important finding of this work is the detection of overexpressed UCA1 in extracellular vesicles namely exosomes, which opens the possibility to use this lncRNA as a circulating biomarker for cisplatin-resistance in women with ovarian cancer." (PMID 34204094, 2021). "Especially, FEZF1-AS1 and UCA1 are detected in serum and exosomes recovered from serum of ovarian cancer patients, respectively, which suggested their potential as liquid biopsy markers for ovarian cancer." (PMID 33996797, 2021). "In this study, UCA1 was identified as promoting the chemoresistance of ovarian cancers." (PMID 34160887, 2021). "Via binding to the 3′-UTRs of FOS-like 2 (FOSL2), miR-143 can negatively regulate FOSL2 expression, suggesting that the UCA1/miR-143 axis may have potential therapeutic value for the treatment of cisplatin resistance in ovarian cancer patients." (PMID 34512721, 2021). "seRNA UCA1 highly expresses in various cancers including gastric and ovarian cancer." (PMID 32278350, 2020). "Urothelial cancer-associated 1 (UCA1), a long non-coding RNA highly specific to Bladder transitional cell carcinoma (TCC), was proved to have a close relationship to colorectal, gastric, ovarian cancer and NSCLC." (PMID 28978188, 2017). "An investigation has shown the elevated expression of UCA1 in ovarian cancer tissues and revealed that the expression of UCA1 RNA in SKOV-3 cells could increase the cell migration, invasion, and cisplatin resistance of these cells." (PMID 27664137, 2017). "Similarly, UCA1 is significantly up-regulated with taxol-resistant ovarian cancer." (PMID 33499129, 2021). "Two different groups reported a higher amount of UCA1, a lncRNA previously involved in cisplatin resistance, in Paclitaxel resistant cells, suggesting that this lncRNA may have a central role in drug resistance in ovarian cancer." (PMID 34204094, 2021). "For example, studies have found that overexpression of lncRNA UCA1 in ovarian cancer cell line SKOV3 increases cellular cisplatin resistance, the mechanism of which may involve overexpression of RPK1 and subsequent dysregulation of the apoptotic pathway related protein." (PMID 32943985, 2020). "UCA1 also enhanced the cell-to-cell spread of OVV via the activation of Cdc42, a Rho GTPase, resulting in better therapeutic outcomes in ovarian cancer." (PMID 38558795, 2024). "LncRNA UCA1 has been reported to enhance paclitaxel resistance via targeting the miR-654-5p and SIK2 in ovarian cancer." (PMID 36105363, 2022). "At the core of the molecular mechanism of these changes is that lncRNA UCA1 negatively affects the expression of miR-143, which in turn is a modulator of FOS-like 2, AP-1 transcription factor subunit (FOSL2) expression in ovarian cancer cells." (PMID 36139487, 2022). "Previous studies found that both UCA1 and GAS5 lncRNAs play roles in the development of ovarian cancer." (PMID 35901079, 2022). "Mechanistically, UCA1 can sponge miR-129 and increase the expression of ABCB1, contributing to paclitaxel resistance in ovarian cancer." (PMID 36105363, 2022). "In two other ovarian cancer cell lines, OAW42 and OVCAR3, both sensitive to cisplatin treatment, UCA1 expression levels were around 100‐ and 200‐fold lower respectively than in OAW42‐R." (PMID 34160887, 2021). "We however showed that miR‐27a‐5p transfection mimics UCA1‐induced BIM induction, which we have shown to be a necessary condition for ovarian cancer cell sensitization to cisplatin." (PMID 34160887, 2021).
ovarian carcinoma (continued). "It was suggested that the regulation of some long non-coding RNAs, such as HOTAIR, UCA1, HOXA11AS, etc., through RNAi techniques or CRISPR/Cas-9 was thought to be a promising therapy for ovarian cancer." (PMID 34765618, 2021). "Other lncRNAs have also been shown to be associated with ovarian cancer development and metastasis, including HOTAIR, H19, GAS5, and UCA1; however, to date, little was known about linc-ROR in ovarian cancer." (PMID 29050257, 2017). "Another study revealed that lncRNA UCA1 expression was positively correlated with SEs and has been identified as a regulator of the Hippo-YAP signaling pathway, highlighting the role of the UCA1-AMOT-YAP signaling axis in ovarian cancer progression." (PMID 37501079, 2023). "Moreover, UCA1 sponged the miR-654-5p and upregulated the expression of its target SIK2 in ovarian cancer cells." (PMID 36105363, 2022). "We would not expect to see the upregulation of UCA1 in chemo-naïve patients, as our study only used samples from ovarian cancer patients at initial diagnosis." (PMID 33499129, 2021). "Overexpression of UCA1 was shown to increase cisplatin resistance in ovarian cancer cells, possibly through the upregulation of SRPK1 expression, a splicing factor whose role in the cisplatin resistance of ovarian carcinoma cells remains controversial." (PMID 26992233, 2016).
pancreatic cancer (42 papers, 2017 to 2025). "UCA1 (urothelial carcinoma-associated 1), a long non-coding RNA, has been extensively studied for its oncogenic functions in pancreatic cancer." (PMID 41080752, 2025). "LncRNA UCA1 is known to be associated with gemcitabine resistance in hypoxic pancreatic cancer cells." (PMID 36499136, 2022). "In serum EVs of pancreatic carcinoma patients, UCA1 levels were associated with poor patient survival." (PMID 35966580, 2022). "A few of these genes have been identified previously in recent studies, among which the most reported one is UCA1, which is highly expressed in pancreatic cancer and is associated with the prognosis of this disease." (PMID 34134622, 2021). "Knockdown of UCA1 inhibits cell proliferative activities, induces cell apoptosis, and causes cell cycle arrest in patients with pancreatic cancer." (PMID 29516678, 2018). "It has been reported that hypoxia in pancreatic cancer triggers the activation of pancreatic stellate cells (PSCs), leading to the secretion of exosomes enriched in lncRNA urothelial carcinoma-associated 1 (UCA1)." (PMID 38911968, 2024). "Moreover, deregulated expression of the long non-coding RNA (lncRNA) UCA1 has been implicated in diverse human cancers, such as pancreatic cancer." (PMID 31185650, 2019). "The published article titled “UCA1 Regulates the Growth and Metastasis of Pancreatic Cancer by Sponging miR-135a” has been retracted from Oncology Research, Vol." (PMID 40918469, 2025). "In particular, MAPK/ERK signalling was shown to be positively regulated by UCA1, which increased mitochondrial dynamics and thereby affected the migratory ability of pancreatic cancer cells." (PMID 40427100, 2025). "In conclusion, UCA1 acted as an oncogene in pancreatic cancer by partly regulating miR-582-5p/BRCC3, which promoted cell proliferation, migration, and inhibited apoptosis." (PMID 37564930, 2023). "A large sample study also confirmed the higher expression of UCA1 in the pancreatic cancer tissues by qRT-PCR." (PMID 37564930, 2023). "In depleted cells, UCA1 acts as an exosomal lncRNA to promote angiogenesis in pancreatic cancer via the miR-96-5p/AMOTL2 axis." (PMID 36871072, 2023). "The aim of this study is to explore and reveal the regulatory effect and mechanism of UCA1 in pancreatic cancer through in vitro and in vivo experiments." (PMID 37564930, 2023). "All three experiments confirmed that downregulation of UCA1 in pancreatic cancer cells by siRNA suppressed cell proliferation and reduced viability." (PMID 37564930, 2023). "Despite this, few details about UCA1 in pancreatic cancer are known, the regulatory role and mechanism of UCA1 are still unclear." (PMID 37564930, 2023). "Compared with pancreatic cancer cells with si-UCA1 alone, cells were cotransfected with si-UCA1 and miR-582-5p inhibitors showed increased proliferation and metastasis, and decreased apoptosis." (PMID 37564930, 2023). "Survival analysis indicated that high expression of UCA1 was an unfavorable prognosis factor for pancreatic cancer." (PMID 37564930, 2023). "Even so, little was known about the function and regulatory mechanisms of UCA1 in pancreatic cancer." (PMID 37564930, 2023). "Compared with pancreatic cancer cells with UCA1 inhibitors only, cells were co-transfected with si-UCA1 and pc-BRCC3 (a plasmid for upregulation of BRCC3) showed increased cell proliferation and metastasis, and decreased in apoptosis." (PMID 37564930, 2023). "The effects of UCA1 on the migration and invasion of pancreatic cancer cells were examined using a wound healing assay and a transwell assay." (PMID 37564930, 2023). "reviewed the functions and pointed out the importance of UCA1 in pancreatic cancer, who showed that UCA1 contributed to carcinogenesis, angiogenesis, and drug resistance via several signal pathways." (PMID 37564930, 2023). "UCA1 promotes cell proliferation and suppresses apoptosis by interacting with miR-135a in pancreatic cancer." (PMID 37245177, 2023).